DTWD2 (DTW motif tRNA-uridine aminocarboxypropyltransferase 2)
Description:
Catalyzes the formation of 3-(3-amino-3-carboxypropyl)uridine (acp3U) at position 20a in the D-loop of several cytoplasmic tRNAs (acp3U(20a)). Also has a weak activity to form acp3U at position 20 in the D-loop of tRNAs (acp3U(20)). Involved in glycoRNA biosynthesis by mediating formation of acp3U, which acts as an attachment site for N-glycans on tRNAs. GlycoRNAs consist of RNAs modified with secretory N-glycans that are presented on the cell surface.
Synonyms: FLJ33977
Tractability: PROTAC: ubiquitination databases record sites on it.
Gene: Protein-coding gene on chromosome 5 (118,836,074 to 118,988,554, reverse strand). Ensembl gene ENSG00000169570.
Subcellular location: Cytoplasm (Isoform 1); Nucleus (Isoform 2); Cytoplasm
Subcellular location (Human Protein Atlas): Nuclear bodies
Gene Ontology:
Molecular function: tRNA-uridine aminocarboxypropyltransferase activity
Biological process: glycoRNA biosynthetic process; tRNA modification
Cellular component: cytoplasm; nucleus
Genetic constraint (gnomAD): Loss-of-function variants: 36 observed, 27.65 expected, observed/expected ratio (o/e) 1.3, 90% interval 1 to 1.71. The synonymous counts are far from expectation, so gnomAD's model fits this gene poorly and the ratio says little. Missense variants: 515 observed, 363.77 expected, observed/expected ratio (o/e) 1.42, 90% interval 1.32 to 1.52. Synonymous variants: 180 observed, 131.7 expected, observed/expected ratio (o/e) 1.37, 90% interval 1.21 to 1.55.
Homologues: Orthologues: chimpanzee DTWD2 (99% identical), macaque DTWD2 (97% identical), pig DTWD2 (87% identical), dog DTWD2 (86% identical), guinea pig DTWD2 (85% identical), mouse Dtwd2 (85% identical), rat Dtwd2 (70% identical), rabbit DTWD2 (69% identical), tropical clawed frog dtwd2 (65% identical), zebrafish dtwd2 (56% identical), Drosophila melanogaster Dtwd2 (35% identical).
Diseases named in the same sentence as DTWD2 in open-access papers:
DTWD2 is named in the same sentence as 10 diseases in open-access papers, as found by Europe PMC text mining. Sharing a sentence is not in itself a finding about the gene and the disease. The quoted sentences say what the papers report.
scrub typhus (2 papers, 2021 to 2023). Scrub typhus is a rare dust mite-borne infectious disease caused by the Orientia tsutsugamushi bacterium and characterized clinically by an eruptive fever which is potentially serious. "Rs2059950 of the DTW domain containing 2 (DTWD2) gene and rs74744256 of the one cut homeobox 1 (ONECUT1) and WD repeat domain 72 (WDR72) gene also showed a significant association of scrub typhus with p < 1 × 10−5." (PMID 33807835, 2021).
Anxiety (1 paper, 2019). Intense feelings of nervousness, tension, or panic often arise in response to interpersonal stresses. "Of interest for our study, polymorphism in DTWD2 has shown to interact with FKBP5 in trans and GABBR1 has been associated with DNA methylation changes in newborns following maternal anxiety during pregnancy." (PMID 31040859, 2019).
bipolar disorder (1 paper, 2019). A disorder of the brain that causes unusual shifts in mood, energy, activity levels and the ability to carry out day-to-day tasks. "Furthermore, a subunit for GABA receptor 1B (GABBR1), DTW Domain Containing 2 (DTWD2), and DISC1-Binding Zinc-Finger Protein (ZNF365), have been associated with multiple often comorbid disorders, including addiction, bipolar disorder, and schizophrenia." (PMID 31040859, 2019).
colon adenocarcinoma (1 paper, 2023). "DTWD2 was downregulated in colon adenocarcinoma and associated with poor prognosis." (PMID 37745798, 2023). "Here, we aimed to initially investigate the expression and role of DTWD2 in colon adenocarcinoma." (PMID 37745798, 2023).
colon cancer (1 paper, 2023). "Cellular experiments and xenografts were also performed to validate the role of DTWD2 in colon cancer progression." (PMID 37745798, 2023). "Finally, cellular and xenograft data demonstrated that silencing DTWD2 significantly enhanced colon cancer growth." (PMID 37745798, 2023). "Furthermore, Cox regression analysis demonstrated that DTWD2 is a novel independent prognostic factor for colon cancer patients." (PMID 37745798, 2023). "Low expression of DTWD2 may be a potential molecular marker for poor prognosis in colon cancer." (PMID 37745798, 2023).
ear infection (1 paper, 2025). A viral or bacterial infection that affects the external, middle, or inner ear. "Interestingly, an eQTL variant (rs421765) for DTWD2 and DMXL1 has also been associated with severe otitis media (severe ear infection) in Aboriginal Australians." (PMID 40725187, 2025).
cancer (1 paper, 2023). A tumor composed of atypical neoplastic, often pleomorphic cells that invade other tissues. "Here, we initially discovered the significant role of DTWD2 in human cancer." (PMID 37745798, 2023). "Dysregulated expression of DTWD1 has been reported in several malignancies, nevertheless, the role of DTWD2 in cancers remains completely unknown." (PMID 37745798, 2023).
tumor (1 paper, 2023). "Furthermore, multiple-omic strategies will be essential to map and elucidate the detailed signaling network of DTWD2 in tumor cells." (PMID 37745798, 2023). "Second, despite our data confirming the tumor-suppressing effects of DTWD2 in COAD cells and mice models, its detailed signaling mechanisms remain unclear." (PMID 37745798, 2023). "DTWD2 inhibits COAD progression by suppressing tumor growth both in vitro and in vivo." (PMID 37745798, 2023). "Low expression of DTWD2 in tumor tissues predicts worse clinical outcomes of COAD." (PMID 37745798, 2023). "Nevertheless, low DTWD2 expression showed significant crosstalk with larger tumor size (P = 0.002), implying that DTWD2 may participate in tumor growth." (PMID 37745798, 2023). "Therefore, the tumor-related role of DTWD2 in more malignancy types deserves further investigation." (PMID 37745798, 2023).
DTWD2 also shares sentences with these, for which no sentence is quoted: otitis media (1 paper); schizophrenia (1).